AQP1 (aquaporin 1 (Colton blood group))
Diseases named in the same sentence as AQP1 in open-access papers (continued):
Sharing a sentence is not in itself a finding about the gene and the disease.
adenoid cystic carcinoma (3 papers, 2018 to 2024). A malignant tumor arising from the epithelial cells. "In adenoid cystic carcinoma it has been noted that AQP1 promoter hypomethylation is common, additionally, AQP1 tends to be overexpressed." (PMID 30555637, 2018). "However, AQP1 promoter hypermethylation has been reported to be widespread in adenoid cystic carcinoma, with the overexpression of AQP1." (PMID 38336645, 2024).
Arthritis (3 papers, 2019 to 2024). Inflammation of a joint. "Concomitantly with the shrinkage of the stably present SLSFs, we observed the emergence of arthritis-specific Thy1+ SF subpopulations (Dkk3/Lrrc15+ and Birc5/Aqp1+), accompanied by expansion of Prg4high/Thy1-LSFs." (PMID 35879783, 2022). "Acetazolamide, AQP1 inhibitor, was decreased AQP1 protein level via inhibition of NF-κB activation and subsequent reduction of hind pow swelling in adjuvant-induced arthritis rats, suggesting that attenuation of AQP1 mediates anti-arthritis effect." (PMID 31480869, 2019).
Ascites (3 papers, 2021 to 2025). Accumulation of fluid in the peritoneal cavity (between the layers of the peritoneum that lines the abdomen). "This demonstrated that the activation of MAPK signaling pathway was involved in organ damage in the “liver-peritoneum-kidney” axis of cirrhotic ascites rats and was associated with AQP1." (PMID 35399826, 2022). "TDEE and its diterpenoids can inhibit the reabsorption and concentration of water in the kidneys by reducing the expression levels of AQP1, AQP2, AQP3 and AQP4, thereby resolving ascites." (PMID 33578967, 2021). "Second, AQP1 expression in LSECs increased significantly in cirrhotic rats with ascites compared with cirrhotic rats without ascites." (PMID 41034523, 2025). "Interestingly, AQP1 expression in the peritoneum increased significantly in cirrhotic rats with ascites compared with cirrhotic rats without ascites." (PMID 41034523, 2025).
benign intracranial hypertension (3 papers, 2010 to 2023).
cholangiocarcinoma (3 papers, 2018 to 2022). A carcinoma that arises from the intrahepatic biliary tree (intrahepatic cholangiocarcinoma) or from the junction, or adjacent to the junction, of the right and left hepatic ducts (hilar cholangiocarcinoma). "Conversely, in clinical cases of cholangiocarcinoma, high AQP1 expression has been correlated with low metastasis, suggesting that AQP1 might play different roles in different types of cancers." (PMID 29922644, 2018).
chronic kidney disease (3 papers, 2018 to 2021). Impairment of the renal function secondary to chronic kidney damage persisting for three or more months. "Although several studies have shown that release of water channel proteins, aquaporin 1 (AQP1) and AQP2 in urinary extracellular vesicles (uEV‐AQP1 and ‐AQP2), were altered in experimental kidney injury models, their release in human chronic kidney disease (CKD) has been largely unexplored." (PMID 34435473, 2021).
COVID-19 (3 papers, 2021 to 2023). A disease caused by infection with severe acute respiratory syndrome coronavirus 2. "An upregulation of proinflammatory cytokines including TNF, IL-6, and IL-10 indicates the activation of a specific immune pathway probably leading to a decrease of AQP1 in patients suffering from COVID-19." (PMID 33918079, 2021). "Finally, serum levels of Aqp1, which is a molecule expressed in alveolar epithelial cells and microvascular endothelial cells, and has been found to increase in patients with COVID-19 compared to healthy controls, were normalized in our long COVID population." (PMID 37763119, 2023). "Our findings on AQP1 support earlier findings showing that AQP1 levels decreased in lung endothelial cells in a humanized animal model of SARS-CoV-2, and strongly suggest the usefulness of our model to study COVID-19." (PMID 35712703, 2022).
cutaneous melanoma (3 papers, 2018 to 2022). A primary melanoma arising from atypical melanocytes in the skin. "AQP1 expression has also been associated with an adverse prognosis in cutaneous melanoma." (PMID 30555637, 2018). "A reduced progression-free and overall survival for the AQP1 positive cutaneous melanoma patients has been reported." (PMID 30555637, 2018).
emphysema (3 papers, 2014 to 2024). "SERPINF1 and ISM1 protect against emphysema formation, whereas AQP1 promotes eosinophilic infiltration." (PMID 38203236, 2023). "Regarding the genes regulating angiogenesis, SERPINF1 and ISM1 upregulation protect against emphysema formation, whereas AQP1 upregulation promotes eosinophil infiltration." (PMID 38203236, 2023). "Statistical analysis revealed a significant correlation between S100β and Hps70 immunoexpression and cerebral pathological features, between ICAM-1 immunoexpression and alveolar edema and pulmonary emphysema, and between AQP-1 immunoexpression and pulmonary emphysema." (PMID 38611652, 2024). "Additionally, no statistical correlation was found between AQP1 immunoexpression and lung pathological features, with the exception of pulmonary emphysema (r = −0.27, p = 0.045)." (PMID 38611652, 2024). "Although the relation between fibrosis and emphysema was not the main focus of this study, we believe that the current findings may stimulate further studies on the potential role played by AQP1 expressed in type 2 pneumocytes in the pathogenesis of the fibrosis/emphysema phenotype." (PMID 24917931, 2014).
esophageal cancer (3 papers, 2018 to 2021). A primary or metastatic malignant neoplasm involving the esophagus. "Overexpression of AQP1 and AQP5 was associated with poor prognosis in lung and esophageal cancers and soft tissue sarcomas." (PMID 32075009, 2020). "This research aimed to determine the roles of AQP1 in the control of tumorigenesis-related genes and its clinical meaning in esophageal cancer." (PMID 30042826, 2018). "According to the result of immunohistochemistry, we hypothesized that tumor cells possessed different types of AQP1 phenotype in ESCC tissues and that it may affect the prognosis of esophageal cancer." (PMID 30042826, 2018).
hypertrophic cardiomyopathies (3 papers, 2022 to 2025). "Deletion of Aqp1 or blockade of AQP1 could present a promising avenue for the treatment of hypertrophic cardiomyopathies." (PMID 39180980, 2024). "Recent breakthroughs indicate that inhibition of hydrogen peroxide permeation through AQP1 provides a new approach to treat hypertrophic cardiomyopathies, and inhibition of AQP4 localization with the licensed drug trifluoperazine provides compelling evidence for a new approach to treating CNS edema." (PMID 35898407, 2022).
liver fibrosis (3 papers, 2018 to 2022). "The same study indicated that with liver fibrosis patients, the AQP1 rs1049305 CC genotype was associated with lower serum sodium concentration and lower serum osmolality when compared to patients with a CG or GG genotype." (PMID 31486928, 2019).
malaria (3 papers, 2015 to 2022). Malaria is a serious and sometimes fatal disease caused by a parasite that commonly infects a certain type of mosquito which feeds on humans. "We showed that ART4 and AQP1 polymorphisms exhibit significant associations with severe malaria and parasite density and that protective allele in both loci occur with higher frequency in populations of African descent compared to those of European descent." (PMID 34880413, 2021). "We also found that genetic variants in both ART4 and AQP1 are associated with susceptibility to the disease in a malaria-endemic population." (PMID 34880413, 2021). "Moreover, genetic variations at both the ART4 and AQP1 loci are significantly associated with severe malaria and parasite density in children from a Sub-Saharan African malaria-endemic country." (PMID 34880413, 2021). "Significant signals of associations are also observed in different regions of the AQP1 gene and an intronic region of only ~500 bp (7:30937178–30937725) harbors variants showing highly significant associations with both severe malaria and parasite density." (PMID 34880413, 2021). "The correlation between the expression of these markers, histopathological and clinical parameters was evaluated to determine whether IL-33, any distinct subtypes of host leukocytes, γ-ENaC, and AQP-1 and -5 were associated with the development of PE in severe malaria lung injury." (PMID 26437894, 2015). "The study further investigated the expression of AQP-1 in CPECs in malaria, which demonstrated the diminished expression of AQP-1 in the CM group." (PMID 35151337, 2022). "The expression of leukocyte sub-set antigens, bronchial interleukin (IL)-33, γ-epithelium sodium channel (ENaC), aquaporin (AQP)-1 and -5, and control cytokeratin staining was quantified in the lung tissue of severe malaria patients." (PMID 26437894, 2015). "The expression levels of alveolar AQP-1 and -5 scoring and bronchial cytokeratin were not significantly different between severe malaria patients with or without PE and healthy subjects." (PMID 26437894, 2015). "However, a study on the lungs of patients with malaria showed that AQP-1 and -5 have no roles in decreasing cellular permeability." (PMID 35151337, 2022). "Moreover, reduced levels of the epithelial sodium channel γ-ENaC but not AQP-1 and -5, were seen, which may retard fluid clearance from the lung and contribute to oedema in severe malaria." (PMID 26437894, 2015).
meningioma (3 papers, 2013 to 2021). A generally slow growing tumor attached to the dura mater. "AQP1 is also present in most meningioma cells and in all capillaries." (PMID 34988012, 2021). "Five genes that were down-regulated in the meningiomas compared to the control tissue included AQP1 (aquaporin 1), FRZB (Frizzled b), PECAM1 (platelet and endothelial cell adhesion molecule 1), PDGFRL (platelet-derived growth factor receptor-like), and FBLN2 (fibulin 2)." (PMID 29073243, 2017). "It is implied that AQP1 and NKCC1 contribute to meningioma biology and invasion." (PMID 34988012, 2021). "AQP1, FRZB, PDGFRL, and PECAM1 were consistently underexpressed in meningioma samples; MEDAG, MYC, PAMR1, PDPN and PERP were consistently overexpressed in nearly every meningioma sample by both measurements." (PMID 29073243, 2017). "Although the co-localization of AQP1 with ion channels on CNS astrocytes has not been studied so far, AQP1 is known to co-localize with the Na-K-2Cl cotransporter in meningiomas, and with the α-epithelial Na(+) channel in the lung." (PMID 24252214, 2013). "There is extensive NKCC1 but no Aquaporin 1 (AQP1) presence in the arachnoid granulation cells, and widespread immunohistochemical staining of NKCC1 in meningioma cells and in capillaries." (PMID 34988012, 2021).
metastatic carcinoma (3 papers, 2002 to 2024). A carcinoma which has spread from the original site of growth to another anatomic site. "In all metastatic carcinomas, AQP1 was expressed in microvessel endothelium and reactive astrocytes." (PMID 12237771, 2002). "In metastatic carcinomas, AQP1 was present in microvessel endothelia and reactive astrocytes." (PMID 35847914, 2022).
multiple sclerosis (3 papers, 2016 to 2025). A progressive autoimmune disorder affecting the central nervous system resulting in demyelination. "Interestingly, increased expression of AQP1 has been found in reactive astrocytes of several neurodegenerative diseases including Creutzfeldt-Jakob disease, multiple sclerosis, and AD." (PMID 32192109, 2020).
myocardial ischemia (3 papers, 2015 to 2025). A disorder of cardiac function caused by insufficient blood flow to the muscle tissue of the heart. "Cardiac ischemia caused by hypoxia secondary to AQP1 deficiency stabilized the expression of HIF-1α in endothelial cells and subsequently decreased microvascular permeability, resulting in the development of edema." (PMID 26348407, 2015). "Recent studies have implicated AQP1 as a mediator of cardiac damage in the setting of both myocardial ischemia and edema." (PMID 26348407, 2015). "Research has shown that myocardial ischemia and infarction can activate AQP1, disrupting the cytoskeletal integrity of cardiomyocytes and increasing the fragility of the myocardial membrane." (PMID 40723374, 2025). "Although little is known about the impact of aging on AQP1 expression in vascular cells, studies showed increased AQP1 expression in cardiac myocytes during aging, contributing to myocardial ischemia in the elderly." (PMID 39180980, 2024). "Our results suggest that AQP1 inhibitors may represent a novel therapeutic target in the modulation of cardiac function in the setting of myocardial ischemia and injury." (PMID 26348407, 2015).
non-small cell lung carcinoma (3 papers, 2008 to 2025). A group of at least three distinct histological types of lung cancer, including non-small cell squamous cell carcinoma, adenocarcinoma, and large cell carcinoma. "Previously, we have provided evidence for novel oncogenic properties of AQP1 and its expression in resected tissue samples from non small cell lung cancer." (PMID 18478076, 2008). "How does AQP1 impact the process of non-small cell lung cancer (NSCLC) angiogenesis?" (PMID 39440058, 2024).
Obesity (3 papers, 2024 to 2025). Accumulation of substantial excess body fat. "Targeted modulation of AQP1 expression provides a therapeutic approach for obesity management and fat deposition control." (PMID 41306337, 2025). "AQP1 in human visceral adipocytes was suggested to serve as a compensatory mechanism to alleviate endoplasmic reticulum stress in obesity." (PMID 38451099, 2024).
oligohydramnios (3 papers, 2016 to 2023). A lower than normal quantity of amniotic fluid in the amniotic sac as compared to normal values. "Furthermore, AQP9 expression was associated with AQP1 level in the placenta and foetal membranes in oligohydramnios." (PMID 32542408, 2020). "The expression of AQP1 protein in the amniotic membrane of isolated oligohydramnios was increased compared with normal pregnancy." (PMID 37386378, 2023). "Compared with patients with a normal AFV, patients with oligohydramnios exhibited dramatically decreased AQP1 and AQP9 expression in the foetal membrane and placental trophoblasts (P < 0.05)." (PMID 32542408, 2020). "In patients with oligohydramnios, AQP9 expression was positively associated with AQP1 expression in both placental trophoblasts (P < 0.05, r = 0.640) and foetal membranes (amnion epithelial cells and chorion cytotrophoblasts) (P < 0.05, r = 0.634)." (PMID 32542408, 2020). "Therefore, AQP1 protein expression in the amniotic membrane was increased in pregnant women with isolated oligohydramnios." (PMID 37386378, 2023). "In this study, patients with oligohydramnios were chosen to determine whether the expression levels of AQP1 and other AQPs are correlated when AQP1 and other AQPs are decreased." (PMID 32542408, 2020). "In our previous study, AQP1 and AQP9 expression in the amnion was decreased in pregnancies with isolated oligohydramnios, so pregnancies with oligohydramnios and a normal AF volume were selected to establish the correlation between AQP1 and AQP9 protein expression." (PMID 32542408, 2020). "Moreover, the correlation among the protein expression of AQP1 and other AQPs in the placenta and foetal membranes of patients with isolated oligohydramnios were also explored using an immunohistochemical method." (PMID 32542408, 2020). "However, an association between expression of AQP1 and other AQPs in patients with a normal AF volume and patients with isolated oligohydramnios has not been established." (PMID 32542408, 2020). "The expression and location of AQP1 and other AQPs in the placenta and foetal membranes of AQP1−/− mice, AQP1-siRNA transfected WISH cells and oligohydramnios patients were also detected." (PMID 32542408, 2020). "Therefore, this study first identified the differences in AQP1 and AQP3 protein expression between the women with normal pregnancy and those with isolated oligohydramnios." (PMID 37386378, 2023). "Compared with normal AFV group, AQP1 protein expression in hAECs was significantly increased in the isolated oligohydramnios group, while AQP3 protein expression was not significantly different." (PMID 37386378, 2023). "Interestingly, in hAECs from pregnant women with isolated oligohydramnios, Tanshinone IIA decreased AQP1 protein expression and increased expression of AQP3." (PMID 37386378, 2023). "However, in oligohydramnios patients, AQP9 expression in the placenta and foetal membranes was positively correlated with AQP1 expression in both placental trophoblasts and amnion epithelial cells." (PMID 32542408, 2020). "Therefore, Tanshinone IIA decreased the expression of AQP1 and AQP3 in hAECs from pregnant women with normal AFV, and Tanshinone IIA decreased AQP1 protein expression and increased the AQP3 expression in hAECs from pregnant women with isolated oligohydramnios." (PMID 37386378, 2023).
optic neuritis (3 papers, 2013 to 2023). Optic neuritis is inflammation of the optic nerve, the nerve that carries the visual signal from the eye to the brain.The conditionmay cause sudden, reduced vision in the affected eye(s). "Autoantibodies against AQP1 (AQP1-Abs) were found among patients in the high risk group (characterized by presence of AQP4 autoantibodies with early forms of LETM or optic neuritis) and diagnosed with NMO and/or MS." (PMID 27941618, 2016). "The low female-to-male ratio, the absence of coexisting autoimmune diseases (e.g. MG), and the predominance of LETM (with a low incidence of optic neuritis) in the anti-AQP1-seropositive NMOsd patients are similar to the characteristics of anti-AQP4-seronegative NMOsd." (PMID 24086369, 2013).
pancreatic cancer (3 papers, 2020 to 2025). "AQP1 overexpression has been associated with poor prognoses in breast, lung, colon, prostate, and pancreatic cancers." (PMID 32075009, 2020). "Recently, we reported the modulation of the most cancer-associated AQPs—AQP1, AQP3, AQP5, and AQP9—in paired pancreatic tumors and adjacent healthy tissues from a pancreatic cancer cohort." (PMID 40305202, 2025). "Recently, we assessed the expression of tumor-associated AQPs (AQP1, AQP3, AQP5, and AQP9) in the same pancreatic cancer cohort, revealing AQP1 downregulation in tumor tissues, and AQP3 upregulation in low-invasiveness grade tumors compared to high invasiveness grade pancreatic tumors." (PMID 40305202, 2025). "For that, we cultured a pancreatic cancer cell line, BxPC3, that was screened for AQP expression, revealing high levels of AQP3 and AQP5 expression and much lower levels of AQP1 and AQP8." (PMID 40305202, 2025). "In particular, AQP1, AQP3, and AQP5 enhance the motility and invasiveness of pancreatic cancer by facilitating actin cytoskeleton remodeling, enabling cancer cells to migrate efficiently through tissue barriers." (PMID 40305202, 2025). "In a previous publication, we investigated the prognostic value of AQP transcripts in the same pancreatic cancer cohort and discussed the correlations found among various AQP isoforms (AQP1, AQP3, AQP5, and AQP9)." (PMID 40305202, 2025). "The relative gene expression levels of AQP1, AQP3, AQP5, and AQP9 were analyzed using real-time quantitative PCR (RT-qPCR) in 24 paired pancreatic tumors and adjacent healthy tissues according to variables such as age, gender, and tumor invasiveness and aggressiveness." (PMID 37761834, 2023).
papilloma (3 papers, 2010 to 2017). A benign epithelial neoplasm that projects above the surrounding epithelial surface and consists of villous or arborescent outgrowths of fibrovascular stroma. "AQP1 immunoreactivity remained polarized to the apical membrane in papilloma tissue, but the staining pattern was heterogeneous." (PMID 28184993, 2017).